HSFX2 (heat shock transcription factor family, X-linked 2)
Gene: Protein-coding gene on chromosome X (149,592,512 to 149,595,314, reverse strand). Ensembl gene ENSG00000268738.
Subcellular location: Nucleus; Cytoplasm
Subcellular location (Human Protein Atlas): Nucleoplasm; Cytosol; Plasma membrane
Gene Ontology:
Molecular function: protein binding; DNA-binding transcription factor activity, RNA polymerase II-specific; RNA polymerase II cis-regulatory region sequence-specific DNA binding; DNA-binding transcription factor activity; sequence-specific DNA binding
Biological process: regulation of transcription by RNA polymerase II; regulation of DNA-templated transcription
Cellular component: cytosol; nucleus; chromatin; cytoplasm
Homologues: Orthologues: chimpanzee HSFX2 (98% identical), Caenorhabditis elegans hsf-1 (12% identical), Drosophila melanogaster Hsf (12% identical). Paralogues in human: HSFX1 (100% identical), HSFY1 (28% identical), HSFY2 (28% identical), HSF5 (19% identical), HSF1 (16% identical), HSFX3 (15% identical), HSFX4 (15% identical), HSF4 (14% identical), HSF2 (13% identical).